CASP4 (caspase 4)
Diseases named in the same sentence as CASP4 in open-access papers (continued):
Sharing a sentence is not in itself a finding about the gene and the disease.
lung carcinoma (12 papers, 2013 to 2025). "The results indicated that the genes FADD, TNFRSF1A, CASP9, MLKL, and CASP4 were the risk factor for lung cancer patients (p < 0.05)." (PMID 36874021, 2023). "Because COPD represents a chronic respiratory disease majorly caused by smoking, and that could be a risk factor for lung cancer, the levels of the circulating caspase-4 in the blood of COPD patients (n = 70) were also evaluated." (PMID 29721208, 2018). "Indeed, we found that smokers- and COPD-derived PBMCs treated with air pollutants, such as particulate matter (PM) of ultrafine sizes, were able to release caspase-4, index of higher risk for lung cancer establishment." (PMID 29721208, 2018). "However, our group demonstrated that AIM2 inflammasome could play a pro-carcinogenic role in lung cancer, in that its activation in tumor-associated pDCs leads to high levels of IL-1α which favors lung tumor cell proliferation in a caspase-4-dependent manner." (PMID 34084280, 2021). "In Vitro: Induces apoptosis in A549 and H460 lung cancer cells, with a higher apoptosis rate observed in A549 cells, involving caspase-4 activation and ER stress markers like GADD34 and CHOP." (PMID 41476609, 2025). "The anti-cancer activity of DMC occurs through promoted expression of ER stress-associated proteins HSPA5, DDIT3, ERN1, ATF6A, ATF6B, CASP4 and CAPS12 in human lung cancer NCI-H460 cells." (PMID 36497321, 2022). "BDMC increases ER stress-associated proteins expression such as HSPA5, DDIT3, ERN1, ERN2/IRE-1β, ATF6, ATF6B and CASP4, which results in cell apoptosis in the human lung cancer NCI H460 cell line." (PMID 36497321, 2022). "We proved that caspase-4 is highly present in the blood of both smokers and COPD patients up to lung cancer patients, so that to identify it as a novel diagnostic tool to predict lung cancer establishment." (PMID 34084280, 2021). "We already demonstrated that the murine caspase-11, as well as the human analogue caspase-4, are involved in lung cancer progression." (PMID 34084280, 2021). "In this study, instead, based on the already published concept that caspase-4 is involved in lung cancer establishment and progression, we attempted to evaluate the upstream inflammasome receptor at the crosstalk between smoking-induced COPD and lung cancer." (PMID 34084280, 2021). "In this regard, a recent manuscript demonstrated that caspase-4 can lead to epithelial-mesenchymal transition in lung cancer, further highlighting the importance of our discovery on the role of caspase-4 in lung carcinogenesis in humans." (PMID 33187551, 2020). "In particular, plasma levels of the circulating caspase-4 were five-fold increased in lung cancer patients (95% CI, 2.603–3.372 ng/ml) compared to healthy subjects (95% CI, 0.3994–0.6219 ng/ml)." (PMID 29721208, 2018). "To note, healthy subjects older than 60 still had lower levels of circulating caspase-4 compared to lung cancer patients older than 60 years old, ruling out age-related differences." (PMID 29721208, 2018). "We found that the circulating caspase-4 was three-fold increased (95% CI, 1.331–1.94 ng/ml) compared to healthy subjects (95% CI, 0.3947–0.6197 ng/ml), although at lower levels than in lung cancer patients (95% CI, 2.603–3.372 ng/ml)." (PMID 29721208, 2018). "NOD1 may be an antioncogene of lung cancer, and high expression of caspase-4 is related to poorer survival outcomes, possibly due to the negative regulation of pyroptosis by caspase-4." (PMID 36523974, 2022). "Similarly to what observed in mice, caspase-4 was correlated to the stage of lung cancer in humans in that it induced cell proliferation in a K-Ras, c-MyC and IL-1α dependent manner." (PMID 33187551, 2020). "Although we do not have a follow-up in the likelihood evidence of lung cancer for these subjects and patients, it is likely that the higher levels of the circulating caspase-4 compared to healthy subjects are predictive for a high risk of lung malignancy." (PMID 29721208, 2018).
lung carcinoma (continued). "Among lung cancer cells, caspase-4 was highly expressed in the SSa-sensitive H358 cell line." (PMID 29245990, 2017). "Notably, the activity of ER stress induced caspase-4 was increased in a time-dependent manner in H1299 and A549 lung cancer cell lines after Ching001 treatment." (PMID 23646116, 2013). "Caspase-4 also highly expresses in the blood of both smokers and COPD patients up to lung cancer patients." (PMID 37194062, 2023). "Compared with the control group, the GSDMD, CASP4 and CASP5 expression in PBMCs of lung cancer patients was significantly higher(P < 0.05)." (PMID 37194012, 2023). "One limitation of our study, though, is that the endogenous ligand for caspase-4 in lung cancer is still not identified; however, our data demonstrate that caspase-4/caspase-11 are involved in lung carcinogenesis in humans and mice, respectively." (PMID 33187551, 2020). "The levels of circulating caspase-4 were significantly higher in the plasma of lung cancer patients (LC; n = 125) than healthy non-smoker, non-pathological subjects (H; n = 79)." (PMID 29721208, 2018). "We found that the levels of the circulating caspase-4 in COPD patients was three times higher (95% CI, 1.703–2.995 ng/ml) than healthy subjects, although these levels were still lower than those observed in lung cancer patients." (PMID 29721208, 2018). "No statistical differences of circulating caspase-4 levels were observed in lung cancer patients according to the histotype and stage." (PMID 29721208, 2018). "No statistical differences were observed in the levels of caspase-4 in the plasma of lung cancer patients who were ≤ or ≥ 60 years old." (PMID 29721208, 2018). "In contrast, we found that besides the circulating, tissue levels of caspase-4 could represent a novel manner to diagnose lung cancer, although the ROC curve of the ELISA test on tissues was not as high as in the plasma." (PMID 29721208, 2018). "The levels of tumor-associated caspase-4 were defined as low (<0.377 ng/ml) or high (>0.377 ng/ml) according to the cut-off value that derived from the mean of the tissue levels of caspase-4 from non-COPD, non-lung cancer patients." (PMID 29721208, 2018). "In particular, we found that 72 (72.7%) out of 99 patients were positive to caspase-4, according to a cut-off value of 0.377 ng/ml, which represented the mean value of the 95% CI of non-COPD, non-lung cancer tissues." (PMID 29721208, 2018).
Alzheimer disease (9 papers, 2020 to 2025). A progressive, neurodegenerative disease characterized by loss of function and death of nerve cells in several areas of the brain leading to loss of cognitive function such as memory and language. "Among them, caspase 4 (CASP4) has been associated with many diseases, including inflammatory bowel disease, Alzheimer’s disease, Parkinson’s disease, and various malignancies." (PMID 33584797, 2020). "Caspase-4 plays a similar role in humans as an ER stress-specific caspase and may be associated with Alzheimer’s disease pathogenesis." (PMID 40555741, 2025). "In Alzheimer’s disease, DNA hypomethylation drives caspase-4 overexpression, exacerbating inflammation and amyloid-beta deposition, and contributing to neuroinflammation." (PMID 40555741, 2025). "LPS from Gram-negative bacteria mediated caspase-11 (rodent) and caspases-4 (humans) (caspase-4/11) signaling appears in sepsis 62, diabetes 63, atherosclerosis 64, and Alzheimer's disease 65 in acute and chronic inflammatory conditions." (PMID 39664579, 2024). "CASP4 plays a key role in a variety of diseases such as spinal cord injury and Alzheimer’s disease-related synaptic and behavioral deficits, and its role in tumors seems to be two-fold." (PMID 39075190, 2024). "An Alzheimer's disease study pointed out that Casp4 regulates microglia in a way that increases the pro-inflammatory process." (PMID 36030234, 2022). "Hypomethylation upstream of the caspase-4 transcription start site may augment caspase-4 expression in Alzheimer’s disease, promoting amyloid-beta plaque formation by elevating IL-1β production." (PMID 40555741, 2025). "To further understand the role of CASP4 in the development of AD, we developed a mouse model of AD (5xFAD, five familial Alzheimer’s disease mutations) lacking CASP11." (PMID 38326859, 2024).
asthma (9 papers, 2020 to 2026). "Taken together, these results indicate that there is also an association between caspase-4 and macrophage Dectin-1 expression in patients with asthma." (PMID 38459541, 2024). "Neutrophilic asthma patients showed a marked increase in caspase-4 expression and elevated production of IL-1β and IL-18." (PMID 39795884, 2024). "In asthma patients, a positive correlation was observed between the expression of Dectin-1 on macrophages and caspase-4 (the human homology of caspase-11), and the proportion of neutrophils in induced sputum." (PMID 38459541, 2024). "Our findings identify PGE2 as a negative regulator of caspase-11-driven pyroptosis and implicate caspase-4/11 as a critical contributor to allergic airway inflammation, with implications for pathophysiology of asthma." (PMID 32103022, 2020). "Our findings therefore define a role for caspase-11 in allergic airway inflammation, and support inhibition of caspase-4 as a therapeutic strategy in asthma." (PMID 32103022, 2020). "This work establishes a mechanistic framework for understanding how bacterial sensing machinery may intersect with allergic inflammation during pathophysiological conditions, and suggests that caspase-4 signaling could represent a therapeutic target in asthma." (PMID 41918729, 2026). "Future research must utilize longitudinal birth cohorts to investigate how prenatal exposures (e.g., PM2.5 inducing epigenetic changes in GSDMD) and severe early-life viral infections (e.g., RSV activating caspase-4) prime the immune system for subsequent asthma development." (PMID 41394843, 2025). "Evidence from severe asthma patients reveals upregulated caspase-4 and GSDMD expression." (PMID 41394843, 2025). "Moreover, Dectin-1 expression in macrophages showed a positive correlation with neutrophil inflammation and caspase-4 expression in asthma patients." (PMID 39795884, 2024). "Finally, we also found that caspase-4 was upregulated in alveolar macrophages isolated from asthma patients compared with healthy controls." (PMID 32103022, 2020). "Finally, alveolar macrophages from asthma patients exhibit increased expression of caspase-4, a human homologue of caspase-11." (PMID 32103022, 2020). "The clinical relevance of this pathway is underscored by findings of upregulated caspase-4 and GSDMD in bronchial biopsies from severe asthma patients with recurrent viral exacerbations." (PMID 41394843, 2025). "Finally, in alveolar macrophages, they observed an increased expression of caspase-4, which is a human homologue of mouse caspase-11, suggesting that human caspase-4 and mouse caspase-11 contribute to allergic airway inflammation and are involved in the pathophysiology of asthma." (PMID 36248872, 2022). "In summary, caspase-4/11 noncanonical inflammasomes contribute to the worsening of airway inflammation and the development of asthma, as shown in animal models and human asthma patients." (PMID 39795884, 2024). "Furthermore, the expression of canonical PRGs, such as GSDMB, caspase-4, and NLRP1, was upregulated in the poorly controlled asthma subtype." (PMID 35967302, 2022). "Moreover, among the various phenotypes of asthma, the expression of NLRP3, caspase-1, caspase-4, and other PRGs in neutrophil asthma significantly increases and NLRP3 inflammatory bodies can drive animal asthma models to produce glucocorticoid resistance." (PMID 35967302, 2022). "Additionally, since macrophages play a crucial role in inflammasome activation, further research will be needed to investigate the role of the caspase-4 noncanonical inflammasome in macrophages from asthma patients with various asthma types." (PMID 39795884, 2024). "Agents, such as PGE2, which effectively inhibit caspase-4/11 noncanonical inflammasomes, could serve as potential treatments for asthma." (PMID 39795884, 2024).
asthma (continued). "Notably, cytoplasmic viral components can also activate the non-canonical inflammasome pathway, engaging caspase-4/5 in humans (caspase-11 in mice), which cleaves GSDMD independently of NLRP3, triggering further epithelial barrier disruption and exacerbating viral-induced asthma flare-ups." (PMID 41394843, 2025).
COVID-19 (9 papers, 2021 to 2023). A disease caused by infection with severe acute respiratory syndrome coronavirus 2. "The expression of caspase-4 in the lungs of COVID-19 patients showed an association with the levels of inflammasome activation markers such as caspase-1, IL-1β, IL-6 and IL-18." (PMID 37251383, 2023). "It will be essential to understand the interplay of CASP4/11 with the heterogenous comorbidities and deficiencies that are associated with COVID-19 morbidity and mortality in the human population." (PMID 35588457, 2022). "Finally, F3 expression was elevated in PBMCs from SARS-CoV-2-infected patients compared with healthy controls, in addition to CASP4, confirming the procoagulant genotype associated with COVID-19." (PMID 37316487, 2023). "Overall, CASP4 is highly expressed in the lungs of COVID-19 patients, and CASP11 is similarly increased upon SARS–CoV-2 infection of mice." (PMID 35588457, 2022). "Again, we shall highlight the similarities between activation of caspase-4 in 6OHDA-treated dDCNs and COVID-19-predicted activation of the same caspase." (PMID 35448038, 2022). "Confirming single-cell transcriptome data, neutrophils from COVID-19 patients also showed increased expression of active caspases-1 and caspase-4." (PMID 35799268, 2022). "BCL2L1 and CASP4 were the only genes found to be dysregulated in both COVID-19 and VTE and also correlated with similar pathways in both patient cohorts." (PMID 34071557, 2021). "CASP4, on the other hand, only has overlapping significant canonical pathways with COVID-19 in recurrent VTE." (PMID 34071557, 2021). "On the other hand, CASP4 expression was correlated with over 10 pathways in the same direction for both COVID-19 and recurrent VTE (Figure A2C)." (PMID 34071557, 2021). "Besides NLRP3, other types of inflammasomes that were initially known to interact with dsRNA or bacteria such as AIM-2, caspase-4 and -8 were found to play a role in the inflammation responses during COVID-19." (PMID 37360532, 2023). "Our findings collectively suggest that targeting the CASP11 homolog, human CASP4, during COVID-19 will prevent severe pneumonia, inflammation, tissue damage, and thrombosis as well as accompanying repercussions such as low oxygen, lung failure, need for ventilators, and possibly long-term sequelae." (PMID 35588457, 2022). "Additionally, we found that human lung sections from COVID-19 patients show higher levels of CASP4 staining compared with healthy lung controls, owing to greater numbers of CASP4-positive cells in the infected lung tissue." (PMID 35588457, 2022). "Deficiency of caspase-11, but not GSDMD, an executioner of pyroptosis, reduces disease severity in SARS-CoV-2–infected mice, suggesting that caspase-11 (or caspase-4/5 in humans) may promote disease severity in COVID-19 independently of pyroptosis." (PMID 36419185, 2022). "Therefore, while CASP4 likely functions similarly in COVID-19 and recurrent VTE, its precise role requires further investigation." (PMID 34071557, 2021). "In addition, we predict that caspase-4 plays an independent role in COVID-19-induced cell death." (PMID 35448038, 2022). "Interestingly, CASP4 was found to be upregulated in both COVID-19 and recurrent VTE but downregulated in single VTE, which suggests that the gene could contribute to the development of recurrent VTE." (PMID 34071557, 2021). "Collectively, caspase-4 acted as a master factor mediating NLRP3 inflammasome activation and COVID-19 pathology." (PMID 37251383, 2023). "We mined available clinical data and found that the expression of human CASP4 and CASP5 in COVID-19 testing swab material correlates with the severity of SARS–CoV-2 infection." (PMID 35588457, 2022). "Oxidized phospholipids are reportedly upregulated in patients with COVID-19, and outside the context of COVID-19, they induce cytokine release in a caspase-4/11–dependent manner without requiring GSDMD-dependent cell death." (PMID 36419185, 2022).
COVID-19 (continued). "Overall, our results demonstrate that CASP4/11 promotes detrimental SARS–CoV-2–induced inflammation and coagulopathy, largely independently of GSDMD, identifying CASP4/11 as a promising drug target for treatment and prevention of severe COVID-19." (PMID 35588457, 2022). "From these pathways, we observe that CASP4 functions similarly in recurrent VTE and COVID-19." (PMID 34071557, 2021). "speculated the involvement of the non-canonical inflammasome caspase-4 in COVID-19 inflammatory response due to both caspase-4 and SARS-CoV-2 localization on the endoplasmic reticulum (ER) membrane." (PMID 37360532, 2023). "BCL2L1 is known to be highly upregulated in inflamed tissue, and it was found to be upregulated in COVID-19 and both single and recurrent VTE, while CASP4 directs the noncanonical upregulation of inflammasomes." (PMID 34071557, 2021).
gram-negative bacterial infections (9 papers, 2015 to 2024). Infections caused by bacteria that show up as pink (negative) when treated by the gram-staining method. "In humans, caspase-4 is constitutively expressed by many cells wherein it surveys the cytosol for bacterial LPS to sense Gram-negative bacterial infection." (PMID 37558421, 2023). "The non-canonical pathway results in inflammasome formation mediated by human caspase-4, caspase-5, and mouse caspase-11 (also called caspase-4/11) as a result of Gram-negative bacterial infection." (PMID 35754962, 2022). "While non-classical pathways are mainly mediated by human homologous genes caspase-4, caspase-5 or mouse caspase-11, which can be activated by various Gram-negative bacterial infections." (PMID 34484243, 2021). "Together, these results suggest that hemolysin plays critical roles in promoting caspase-4 activation during Gram-negative bacterial infection." (PMID 30138458, 2018). "In addition, there are different response mechanisms in the response of caspase-4, -5 and -11 to Gram-negative bacterial infection." (PMID 33467535, 2021). "As the function of murine caspase-11 especially in the immune response to Gram-negative bacterial infections becomes increasingly important, establishing functional conservation in human caspase-4 and -5 is critical to understanding this pathway as it relates to human systems." (PMID 26426007, 2015). "The non-canonical inflammasome, comprising murine caspase-11 (or the human orthologs caspase-4/5) and GSDMD, has a protective role against Gram-negative bacterial infection; however, little is known regarding its function in colitis." (PMID 37240022, 2023). "In contrast to caspase-1, caspase-4, -5 and -11 act mainly in response to lipopolysaccharide coming from Gram-negative bacterial infection with the non-canonical inflammasome pathway." (PMID 33467535, 2021). "Recently, the focus of murine caspase-11 and human orthologs caspase-4, -5 research has been on their novel function to induce noncanonical inflammasome activation in direct response to Gram-negative bacterial infection." (PMID 26426007, 2015). "Taken together, our results provide insights into the roles of gram-negative bacteria in gut-generated LPS and intracellular gram-negative bacterial infections in CKD and hyperlipidemia pathologies activating CASP4/11-GSDMD and IL1B pathways." (PMID 39024553, 2024).